SAXO6 (stabilizer of axonemal microtubules 6)
Description:
Microtubule-binding protein that negatively regulates centriole duplication. Binds to and stabilizes microtubules.
Synonyms: MDM1
Tractability: PROTAC: ubiquitination databases record sites on it; its protein half-life has been measured.
Gene: Protein-coding gene on chromosome 12 (68,272,443 to 68,332,381, reverse strand). Ensembl gene ENSG00000111554.
Subcellular location: Nucleus; Cytoplasm, cytoskeleton, microtubule organizing center, centrosome; Cytoplasm, cytoskeleton, microtubule organizing center, centrosome, centriole
Subcellular location (Human Protein Atlas): Centriolar satellite; Cytosol
Gene Ontology:
Molecular function: microtubule binding; protein binding
Biological process: negative regulation of centriole replication; retina development in camera-type eye
Cellular component: centriolar satellite; centriole; centrosome; nucleus
Genetic constraint (gnomAD): Loss-of-function variants: 40 observed, 64.62 expected, observed/expected ratio (o/e) 0.62, 90% interval 0.48 to 0.81. The upper end of that interval is the gene's LOEUF score, 0.81, which puts it in group 3 of 6, group 1 being the genes least tolerant of losing a copy. Missense variants: 688 observed, 737.84 expected, observed/expected ratio (o/e) 0.93, 90% interval 0.88 to 0.99. Synonymous variants: 260 observed, 260.45 expected, observed/expected ratio (o/e) 1, 90% interval 0.9 to 1.11.
Homologues: Orthologues: chimpanzee MDM1 (98% identical), macaque MDM1 (96% identical), rabbit MDM1 (81% identical), dog MDM1 (80% identical), pig MDM1 (74% identical), mouse Mdm1 (70% identical), rat Mdm1 (69% identical), guinea pig MDM1 (69% identical), tropical clawed frog mdm1 (40% identical), zebrafish mdm1 (33% identical).
Diseases named in the same sentence as SAXO6 in open-access papers:
SAXO6 is named in the same sentence as 16 diseases in open-access papers, as found by Europe PMC text mining. Sharing a sentence is not in itself a finding about the gene and the disease.
SAXO6 shares sentences with these, for which no sentence is quoted: cancer (5 papers); tumor (3); infection (2); retinal degeneration (2); Retinal dystrophy (2); bladder cancer (1); breast carcinoma (1); ciliopathies (1); cone-rod dystrophy (1); glioma (1); Hereditary breast cancer (1); melanoma (1); oral carcinoma (1); retinitis pigmentosa (1); sarcopenia (1); vitiligo (1).